PCSK9 (proprotein convertase subtilisin/kexin type 9)
Diseases named in the same sentence as PCSK9 in open-access papers (continued):
Sharing a sentence is not in itself a finding about the gene and the disease.
atherosclerosis (continued). "Both results from MAEC and MCEC lines showed that cells treated with LDb-LDL (containing PCSK9) induced a greater expression of pro-inflammatory and pro-autophagy genes, which are important for atherogenic properties, indicating the key role of PCSK9 in promoting atherosclerosis." (PMID 36005422, 2022). "Furthermore, recent studies suggested a novel role for PCSK9 in promoting atherosclerosis through platelet activation, a key role during atherogenesis and in atherothrombosis-induced MI." (PMID 35207479, 2022). "Furthermore, investigations have revealed that PCSK9 promotes inflammation and platelet activation, in addition to its role in lipid metabolism, which contributes to atherosclerosis." (PMID 36005422, 2022). "Interestingly, subsequent studies then found the ability of PCSK9 to induce atherosclerosis, independently from the LDL-c plasma levels." (PMID 35207479, 2022). "The most successful RNA drug in atherosclerosis is Inclisiran, the siRNA drug targeting PCSK9." (PMID 35548442, 2022). "Therefore, PCSK9 is involved in several pathways promoting atherosclerosis, and for this reason, it has become a target for atherosclerotic dyslipidemia therapies, particularly in patients who have a very-high risk for CVD." (PMID 35683632, 2022). "Very recently, a PCSK9-AAV [pro-protein convertase subtilisin/kexintype 9 (PCSK9) adeno-associated virus (AAV)] was reported as a model for atherosclerosis that does not require genetic modification." (PMID 35648220, 2022). "Furthermore, activation of adiponectin receptors was shown to regulate PCSK9 expression in experimental model of atherosclerosis with direct impact on the disease burden." (PMID 36093150, 2022). "In addition to diagnosis role, in terms of therapeutics in the atherosclerosis field, the most successful RNA drugs in atherosclerosis are proprotein convertase subtilsin/kexin type 9 (PCSK9) inhibitors, a siRNA drug that targets PCSK9 mRNA." (PMID 36505351, 2022). "The major findings of this study bring clear evidence that diet changes and treatment with lipid-lowering drugs (e.g., statins and PCSK9 inhibitors) are not sufficient to stop/ reverse entirely the risk factors for cardiovascular disease in atherosclerosis." (PMID 35181730, 2022). "Therefore, the Yucatan minipig pig as an animal model of atherosclerosis with D374Y-PCSK9 expression can potentially be used for further research in PCSK9 and platelet activation during atherosclerosis disease progression." (PMID 36005422, 2022). "Beyond lipid metabolism, PCSK9 is involved in the development of atherosclerosis, promoting plaque formation in mice and human, impairing the integrity of endothelial monolayer and promoting the events that induce atherosclerosis disease progression." (PMID 35326219, 2022). "Di’ao Xinxuekang (DXXK) capsule, as a well-known traditional Chinese herbal medicine for the prevention and treatment of coronary heart disease, can alleviate lipid disorders and ameliorate atherosclerosis in atherosclerosis model mice and downregulate the expression of PCSK9." (PMID 35571088, 2022). "Apart from lowering LDL-C and by this, preventing the progression of atherosclerosis, possible direct effects of PCSK9 on atherosclerosis and its involvement in inflammation, triglyceride-rich lipoprotein metabolism, platelet activation, cancer, and viral infections have been described." (PMID 35050192, 2022).
atherosclerosis (continued). "Taking these findings together, it may be hypothesized that circulating PCSK9 could be a dangerous enemy of cardiovascular health and its reduction could be beneficial for slowing atherosclerosis progression." (PMID 35454151, 2022). "Therefore, PCSK9 has become one of the most concerned and promising targets of atherosclerosis gene therapy." (PMID 34805315, 2021). "Thus, this intensive lipid-lowering effect of PCSK9 inhibition is still remarkable and stable in HHcy-related atherosclerosis." (PMID 34660746, 2021). "Studies have shown that Pcsk9 may speed up atherosclerosis due to promote inflammation, endothelial cell function and hypertension, and that its mechanism is not related to LDL-R." (PMID 34044829, 2021). "PCSK9 is expressed on aortic ECs, SMCs, macrophages, dendritic cells and epithelial cells, suggesting that PCSK9 not only regulates atherosclerosis by influencing serum LDL-C levels, but also by interacting and influencing cellular processes in the vessel wall to aggravate atherosclerosis." (PMID 34356856, 2021). "Considering that EVs are key players in the initiation of atherosclerosis and lesion progression, the results of the present study portend to a novel role for PCSK9 in regulating the intercellular communication mediated by these lipid bilayer membrane vesicles." (PMID 35071356, 2021). "Given that enhanced circulating levels of LDL-C are crucial not only for the development and the progression but also for the outcomes of atherosclerotic CV disease, therapies including PCSK9 inhibitors are expected to slow the progression of atherosclerosis and reduce CV events and death." (PMID 34070931, 2021). "Furthermore, some studies have demonstrated that the development of atherosclerosis by PCSK9 also correlates with platelet activation, blood pressure regulation and glucose metabolism." (PMID 33738300, 2021). "We will comment on PCSK9 effector roles showing that they extend far beyond the regulation of LDL particles and reveal new insights by which PCSK9 inhibitors may lower the incidence of atherosclerosis progression." (PMID 33834043, 2021). "Contrarily, PCSK9 might provide a protective effect against atherosclerosis progression by regulating SMCs." (PMID 34356856, 2021). "This review will discuss the role of PCSK9 in modulating the activity of different cell lineages involved in atherosclerosis progression including macrophages, vascular smooth muscle cells (VSMC), endothelial cells (EC), lymphocytes and platelets and its associated cardiovascular risk." (PMID 33834043, 2021). "Furthermore, PCSK9 interacts with sortilin in the Trans-Golgi complex, which is a transmembrane protein involved in the development of atherosclerosis and other CVDs, aiding in the extracellular secretion of PCSK9." (PMID 34356856, 2021).
atherosclerosis (continued). "PCSK9 protein has an impact on the metabolism of triglyceride-rich lipoprotein (TRL)—highly atherogenic particles associated with the initiation and propagation of atherosclerosis." (PMID 34199468, 2021). "Indeed, beyond its effects on LDL metabolism, several studies have demonstrated the existence of additional roles of PCSK9 in different stages of atherosclerosis through its interaction with other receptors, such as LRP1, ApoER2, and CD36." (PMID 34070931, 2021). "This work is important for the development of new drugs against PCSK9 that could be administrated to treat heart diseases and control the rising problems related to high cholesterol for atherosclerosis prevention and treatment." (PMID 34351937, 2021). "It was concluded that (S)-canadine may act as a potential inhibitor against atherosclerosis for the development of new PCSK9 inhibitory drugs in future in vitro research." (PMID 34351937, 2021). "Accordingly, a previous study suggested that the serum level of PCSK9 may be useful as a predictive factor for early atherosclerosis, considering that the expression of PCSK9 was high in the plasma of patients with carotid IMT." (PMID 34071276, 2021). "The severity of atherosclerosis is positively correlated with circulating PCSK9 levels." (PMID 34356856, 2021). "This fact could explain the direct relationship between PCSK9 and atherosclerosis and why PCSK9 overexpression is proatherogenic, whereas its absence is protective, adding cardiovascular benefits for anti-PCSK9 therapies." (PMID 34070931, 2021). "Therefore, more in-depth and complex research is needed to thoroughly clarify the mechanism of PCSK9 in Hcy-induced atherosclerosis, to provide more professional evidence for clinical intervention in patients with HHcy-related ASCVD." (PMID 34660746, 2021). "Therefore, combining antithrombotic therapy with PCSK9 inhibitors can have beneficial effects both on platelet activity and atherosclerosis progression." (PMID 34071103, 2021). "According to these findings, mtROS may be a link in the PCSK9-mtDNA interplay, through which PCSK9 expression, mtROS, and mtDNA damage form a positive feedback loop to synergistically facilitate cell injury, thus inducing atherosclerosis." (PMID 32169071, 2020). "A further hypothesis linking PCSK9 to atherosclerosis is the direct role that this protein can play on atherogenesis." (PMID 33143700, 2020). "The purpose of this study was to investigate whether aerobic exercise training inhibits atherosclerosis via the reduction of proprotein convertase subtilisin/kexin type 9 (PCSK9) expression in balloon-induced common carotid arteries of a high-fat-diet rats." (PMID 32325897, 2020). "They found that shRNA acting against PCSK9 significantly inhibited the phosphorylation of p38 and JNK, indicating that PCSK9 promoted the development and progression of atherosclerosis by mediating the apoptosis of endothelial cells via the p38/JNK/MAPK signaling pathway." (PMID 32169071, 2020). "Atherosclerosis was induced in wild type and SPPL2a/b−/− mice via overexpression of a gain-of-function mutant of the Proprotein Convertase Subtilisin/Kexin type 9 (PCSK9) in order to deplete the LDL receptor in combination with a high fat/high cholesterol diet." (PMID 32052089, 2020). "miRs targeting Pcsk9 alleviated hyperlipidemia and atherosclerosis." (PMID 33119548, 2020). "Meanwhile, endothelial cell apoptosis may be repressed through mitogen-activated protein kinase signaling in atherosclerosis by shRNA-PCSK9 targeting of PCSK9." (PMID 33173529, 2020).
atherosclerosis (continued). "PCSK9 has similar roles in atherosclerosis development and increases with age as APOH does." (PMID 32587953, 2020). "Experimental studies have suggested that PCSK9 might directly promote inflammatory processes contributing to atherosclerosis." (PMID 32460779, 2020). "In addition to vascular-specific changes in PCSK9 and their direct contribution to pro-inflammatory processes in the development of atherosclerosis, the indirect effects of PCSK9 in chronic inflammatory processes are also discussed." (PMID 33364976, 2020). "A novel murine model of atherosclerosis, PCSK9 adeno-associated virus mice, was developed without using germline genetic engineering." (PMID 32428130, 2020). "According to other studies, PCSK9 may be a key molecule in the pathophysiology of diseases such as atherosclerosis, myocardial ischemia, Alzheimer’s disease, psoriasis, and fatty liver disease." (PMID 33488522, 2020). "It is imperative to highlight that in addition to controlling the LDL receptor expression and serum LDL levels, PCSK9 appears to play conflicting roles in atherosclerosis development, inflammation, thrombosis, apoptosis, diabetes, obesity, hypertension, and Alzheimer’s disease." (PMID 32587953, 2020). "Thus, PCSK9 is positively correlated with chronic inflammation, which plays an important role in inducing atherosclerosis." (PMID 32169071, 2020). "The proprotein convertase subtilisin/kexin type 9 (PCSK9) has been reported to play an important role in the development of atherosclerosis; PCSK9 monoclonal antibodies (mAbs), including evolocumab and alirocumab, have been put into clinical use to decrease circulating PCSK9." (PMID 32169071, 2020). "The present study demonstrated that the treatment with the anti-PCSK9 antibody mAb1 reduced atherosclerosis development, macrophage infiltration and cardiovascular inflammation and increased the number of EPC and CAC in APOE*3Leiden.CETP mice fed a Western type diet." (PMID 31366894, 2019). "Thus, in accordance with the previous studies, we also concluded that Ginkgolide B exerts protective effect against atherosclerosis via limiting the PCSK-9 expression." (PMID 31281844, 2019). "In mice lack of PCSK9 is protective against atherosclerosis and overexpression of it causes increased accumulation of cholesteryl-esters in aorta leading to accelerated atherosclerosis." (PMID 29770231, 2018). "Besides lipid metabolism and atherosclerosis, several studies have emphasized a possible link between PCSK9 and glucose metabolism." (PMID 29343301, 2018). "Therefore, since its discovery in 2003, PCSK9 has become a research hotspot in the development of new drugs to lower cholesterol and intervene in atherosclerosis." (PMID 30443213, 2018). "To assess whether the differences in cytokine levels between the 2 groups account for vascular inflammation and early atherosclerosis development, we fed WT and Ad-KO mice a WD for 4 weeks after PCSK9 injection to promote atherogenesis." (PMID 29563332, 2018).
atherosclerosis (continued). "In humans, circulating PCSK9 level correlated positively with serum total and LDL-Ch concentration and there are reports suggesting that elevated serum concentration of PCSK9 may play a role in early pathogenesis of atherosclerosis." (PMID 26481479, 2016). "Conversely, overexpression of PCSK9 induced an excess burden of atherosclerosis." (PMID 27095708, 2016). "A growing body of evidence indicated that PCSK9 might influence the serum lipid levels and the progression of atherosclerosis in vitro and in vivo." (PMID 26576960, 2015). "This combination could be a better strategy not only for exerting good lipid-lowering effect on LDL-C, but also for mitigating the adverse effects of lipid-lowering drugs on PCSK9 in controlling dyslipidemia and atherosclerosis." (PMID 24533584, 2014). "These similar findings have been hypothesized to result from a lifetime reduction in LDL-C, reducing the burden of atherosclerosis, but could also be explained if PCSK9 does more than control LDL-R levels." (PMID 25180781, 2014). "Interestingly, co-targeting PCSK9 and IL-1β (e.g., dual vaccination or combination with canakinumab) may synergistically suppress both lipid and inflammatory drivers of atherosclerosis." (PMID 40823653, 2025). "Consequently, elevated levels of PCSK9 may contribute to atherosclerosis by reducing LDL cholesterol clearance." (PMID 39445733, 2025). "In addition to its hepatic functions, PCSK9 also plays important roles in vascular pathophysiology, the expression of PCSK9 in vascular wall cells is indeed directly related to the occurrence of atherosclerosis and aneurysms, as evidenced by multiple studies." (PMID 40764605, 2025). "In vivo studies in apolipoprotein E (apoE) knockout mice revealed that PCSK9 silencing could inhibit the progression of atherosclerosis by reducing vascular inflammation and limiting activation of the TLR4/NF-κB signaling pathway without changing plasma cholesterol levels." (PMID 41368357, 2025). "Similarly, control mice with Pcsk9 overexpression–induced atherosclerosis treated with 10 μg/kg semaglutide for 18 weeks also showed reduced liver inflammation, as confirmed by quantitative PCR analysis of Col1a1, Tnf, Ccl2, Tgfb1, Cd3g, Il2, and Il4 expression." (PMID 41178710, 2025). "We investigated whether CAP1 was required to induce PCSK9-mediated atherosclerosis using a model of partial ligation of the carotid artery to induce D-flow at the distal end15 under high-fat diet conditions in WT and Cap1+/− mice with or without tail vein injection of AdV-PCSK98." (PMID 38555386, 2024). "Therefore, the inhibition of endothelial cell apoptosis by PCSK9 inhibitors may potentially mitigate atherosclerosis and induce plaque regression." (PMID 39767636, 2024). "Besides, Inhibitors of PCSK9 can reduce low-density lipoprotein (LDL) cholesterol levels, potentially decreasing the risk of severe cardiovascular disease symptoms associated with atherosclerosis." (PMID 38895538, 2024).